NF1 (neurofibromin 1)
Diseases named in the same sentence as NF1 in open-access papers (continued):
Sharing a sentence is not in itself a finding about the gene and the disease.
tumor (continued). "We report for the first time, a strong correlation between the NF1 status of tumor cells and increased sensitivity to glutamine deprivation and glutaminase inhibition." (PMID 29212209, 2017). "Loss of tumour suppressors such as phosphatase and tensin homolog (PTEN) and neurofibromin 1 (NF1) has also been linked to aberrant NF-κB activation in GBM, at least in part as a result of increased PI3-kinase (PI3K) activity." (PMID 28598356, 2017). "The basal expression subtype was found to harbour NF1 alterations, suggesting a potential direction for the treatment of such tumours." (PMID 28637487, 2017). "Neurofibromatosis type 1 (NF1; MIM#162200) is a tumour predispositionsyndrome with an incidence at birth of 1 in 2000–3000." (PMID 28213670, 2017). "Further studies are needed to investigate tumor immunosurveillance by Type-I/Type-II NKT cells as well as Tregs in Nf1+/− mice." (PMID 29354122, 2017). "In earlier times, the sometimes extraordinary and large tumor growth in patients who suffered from an unsightly looking disease that is now called NF1 led the treating physicians to coin neologisms to symbolize their visible findings." (PMID 29214122, 2017). "The CD1d-specific antibody treatment in Nf1+/− mice also increased the survival rate of tumor-bearing mice." (PMID 29354122, 2017). "Recently, research data have shown that NF1, surgical margin status, and tumor size are significant predictors of survival in patients with MPNST." (PMID 29285213, 2017). "Thereafter, however, it was shown that NF1 regulates glial cell proliferation and tumor growth in an AKT/mTORC1 dependent but TSC/RHEB independent manner." (PMID 28335463, 2017). "This increased frequency of somatic CDC73 mutations is similar to that occurring for the neurofibromin 1 (NF1) gene, another tumor suppressor, in which somatic non‐synonymous mutations were ∼80‐fold more frequent than germline mutations." (PMID 28881068, 2017). "M1 contains tumours with SDHx mutations and hypermethylation, M2 VHL-mutated tumours, and M3 tumours with NF1 and RET mutations and hypomethylation." (PMID 28327598, 2017). "In previous preclinical studies using NF1-tumor mouse models, both MEK and mTORC1 inhibitors showed tumors growth suppression properties but no cytolytic effect." (PMID 26840085, 2016). "To establish the underlying mechanism of these observations, we performed in vivo structure-function analyses to show that the tumor suppression function of NF1 is mediated through the GAP activity of its GRD domain." (PMID 27130733, 2016). "This latter finding underscores the obligate role of the tumor microenvironment in Nf1 murine low-grade gliomagenesis." (PMID 28066715, 2016). "WHO grade (P = 0.7), tumor location (P = 0.5), tumor size (P = 0.2), NF‐1 status (P = 0.6) and the applied tailored treatment strategy (P = 0.8) did not gain prognostic influence." (PMID 26714663, 2016). "The mitotic counts for NF1-GISTs were lower than those for sporadic GISTs in this study; however, the observed tumor size was similar, contradicting the results of a previous study without a control arm." (PMID 26511941, 2016). "The importance of donating tumor samples for research purposes should be emphasized to medical groups and families – especially for patients affected by NF1-PA, for which surgical biopsy samples are sometimes sparingly small." (PMID 28066715, 2016).
tumor (continued). "Ostensibly, this would seem inconsistent with our current findings in the zebrafish model implicating downregulation of the RAS pathway in NF1-mediated tumor suppression." (PMID 27130733, 2016). "Nf1 is a tumor suppressor gene due to its well-characterized Ras GTPase activating protein related domain (RAS-GRD), which negatively regulates RAS activity by accelerating the hydrolysis of the activated GTP-bound RAS." (PMID 27494873, 2016). "Together, our results support an important role of the tumor suppressor nf1 in restricting both the proliferative rate and survival of MYCN-overexpressing hyperplastic sympathetic neuroblast precursors." (PMID 27130733, 2016). "The mitotic activity of the NF1-GISTs was significantly lower for mitotic counts (/50 HPF) and Ki67-positive tumor cells than that of the non-NF1-GISTs." (PMID 26511941, 2016). "Nevertheless, the sorafenib + rapamycin combination showed far more significant tumor reduction in NF1-related cases than in sporadic cases (Fig7A)." (PMID 25810463, 2015). "The somatic inactivation of the normal allele in PCC/PGL tumour suppressors such as SDHx, VHL and NF1 tumours is driven by large deletions at the corresponding loci, but not by somatic mutations or epigenetic modifications." (PMID 25625332, 2015). "Further, in vitro and in vivo functional studies provided evidence for the tumor suppressor role for Neurofibromin 1 (NF1) gene in different subtypes of LPS." (PMID 26643872, 2015). "Grb10 restoration in Nf1 mutant tumor cells reduced colony formation, proliferation, and suppressed Ras signaling, suggesting Grb10’s tumor suppressive effects are mediated by modulating Ras pathway activation." (PMID 26000738, 2015). "Functionally, restoring Grb10 protein in Nf1 null tumors suppressed tumor growth in a MAPK-dependent mechanism." (PMID 26000738, 2015). "RET, NF1 and sporadic tumours (Cluster C2A) displayed a high frequency of 1q and 3q deletions, and a significant enrichment of 17q11 deletions (NF1 locus)." (PMID 25625332, 2015). "Mutagenizing Nf1+/- and wildtype mice with ionizing radiation generated diverse malignancies from which we generated a unique panel of mouse tumor cell lines." (PMID 26000738, 2015). "Neurofibromin, the protein product of the NF1 tumor suppressor gene, functions as a guanosine triphosphatase-activating protein for Ras." (PMID 25786243, 2015). "The endothelial marker CD34 was shown to be positive in two of the NF1 tumor models (including the corresponding primary tumors) but negative for the rest of cases." (PMID 25810463, 2015). "The internal tumor burden in individuals with NF1 has been studied using T2-weighted whole-body MRI segmentation techniques." (PMID 26625155, 2015). "One tumor showed an inactivating NF1 intragenic deletion as a mechanism for activating the MAPK pathway." (PMID 26440310, 2015). "Short hairpin RNA (shRNA) knockdown of SPP1 in NF1-MPNST cells reduced tumour spheroid size, wound healing and invasion in four different MPNST cell lines." (PMID 25884485, 2015). "In further studies, we provided evidence for a potential tumor suppressor role of NF1 in vitro and in vivo." (PMID 26643872, 2015). "The comparative transcriptome analysis reported here identified the SPP1 gene to be the single most differentially overexpressed gene in NF1-MPNSTs as compared to benign tumours." (PMID 25884485, 2015).
tumor (continued). "We established multiple tumor cell lines from primary radiation-induced tumors, two arising from wildtype mice (cell lines 867 and 963) and ten arising from Nf1+/- mice." (PMID 26000738, 2015). "Integrative exome sequencing, SNP analysis and biological studies revealed tumor suppressor role of Neurofibromin 1 (NF1) in LPS." (PMID 26643872, 2015). "Whilst biallelic NF1 gene inactivation contributes to benign tumour formation, additional cellular changes in gene structure and/or expression are required to induce malignant transformation." (PMID 25884485, 2015). "Tumor progression requires complex interactions between Schwann cells and NF1 heterozygous (NF1+/−) cell lineages in the tumor microenvironment including innate immune system cells." (PMID 25759690, 2015). "Grb10 restoration significantly decreased proliferation by the Nf1 null 881 tumor cells, and to a lesser extent, reduced cell proliferation in V16HRas-transformed human astrocytes." (PMID 26000738, 2015). "Twenty inactivating mutations (PTC and splicing mutations) were also identified in tumor suppressor genes including RB1 (n = 1), NF1 (n = 3) or MLH1 (n = 2)." (PMID 26155992, 2015). "In earlier work, we mutagenized Nf1+/- and control wildtype mice to model second malignant neoplasms, severe complications that individuals with the NF1 syndrome develop can develop after radiotherapy." (PMID 26000738, 2015). "NF1 is a tumor suppressor large gene with 60 exons located on chromosome 17 with described missense, nonsense, and splice-site mutations, indels, and chromosomal rearrangements." (PMID 26347711, 2015). "The present study validated an amplicon based next generation sequencing method for diagnostic re-sequencing of 11 genes (including EPAS1 and NF1) associated with PCC and PGL tumours." (PMID 26230854, 2015). "Several brain abnormalities have been observed in NF1, including neoplasms, T2 hyperintensities (T2H), macrocephaly, and abnormalities in white matter (WM) integrity." (PMID 26473019, 2015). "In vivo stable NF1 knockdown resulted in increased human LPS growth in a NSG xenograft model suggesting a tumor suppressor role of this gene that is frequently aberrant in different types of LPS." (PMID 26643872, 2015). "Expression analysis of these lines revealed decreased Growth factor receptor bound protein 10 (Grb10) mRNA in Nf1 null tumor cell lines compared to controls." (PMID 26000738, 2015). "In fact, subsequent studies have revealed that microglia was an important contributor to tumor growth in the Nf1 model." (PMID 25008045, 2014). "NF1 is considered a classical tumour suppressor gene, with both copies of the NF1 gene reported to be inactivated in benign and malignant tumours in NF1 patients." (PMID 25026295, 2014). "It is possible that the frequency of somatic NF1 alterations in various tumours is higher than what is currently recognized." (PMID 25026295, 2014). "A better understanding of the implications of these aberrations is critical for the improvement of treatment outcomes of tumours with NF1 aberrations." (PMID 25026295, 2014). "Mutations in this gene are inherited in an autosomal dominant fashion and induce tumor development by enhancing the kinase-dependent signaling pathways, similarly to mutated RET and NF1 genes." (PMID 24899893, 2014). "Proportionally more NF1 mutations were found in luminal or ER+HER2- subtypes, although they were also present in selected HER2-overexpressing and triple negative or basal tumours." (PMID 25026295, 2014). "Genetic ablation of microglia, using a CD11b-TK transgenic mouse reduced Nf1 optic glioma proliferation during both tumor maintenance and tumor development." (PMID 25008045, 2014). "Another demonstration of the contribution of microglia to tumor formation came from studies using the Nf1 GEMM." (PMID 25008045, 2014). "Herein, we set out to investigate the feasibility using soluble AXL as a marker to assess NF1 related tumor burden." (PMID 25551830, 2014).
tumor (continued). "In a discovery cohort of 89 self-reported European-Americans with NF1 we examined the association between germline sequence variants of these genes with café-au-lait macule (CALM) count, a tractable, tumor-like phenotype in NF1." (PMID 25329635, 2014). "NF1 is a tumor suppressor regulating signaling from RAS; germline mutations in NF1 deregulate both PI3K and MAPK pathways and result in familial neurofibromatosis." (PMID 24743024, 2014). "Analysis of SNP array data showed loss of heterozygosity (LOH) located to the genomic coordinates of the respective gene in 1/1 SDHB, 11/11 VHL and 3/3 NF1-related tumours." (PMID 24466223, 2014). "Recent next-generation sequencing projects have revealed somatic NF1 aberrations in various sporadic tumours." (PMID 25026295, 2014). "Treatment with Everolimus and PD-901 in combination in the NF1-asssociated mouse model extended lifespan and dramatically reduced tumor burden, although all tumors that were analyzed at necropsy were grade 2, as assessed by H & E, S100, and Ki67." (PMID 24681606, 2014). "Both mouse models had significant reductions in tumor burden when drugs were combined (7.5 tumors per animal in the NF1-asociated model, p <0.0001 and 11.8 tumors per animal in the spontaneous model, p=0.0474)." (PMID 24681606, 2014). "In vitro, the importance of NF1 was demonstrated in NIH 3T3 cells, which when over expressed, displayed a reduction in cell growth compared to untreated cells, further supporting a tumor suppressor role for NF1 via RAS inhibition." (PMID 23335975, 2013). "Our findings identified miR-193b as a potentially novel prognostic marker in HNSCC that drives tumour progression via down-regulating NF1, in turn leading to activation of ERK, resulting in proliferation, migration, invasion, and tumour formation." (PMID 23335975, 2013). "Systematic analysis of the internal tumor load of patients with NF1 by whole-body magnetic resonance imaging (MRI) suggests an association between the risk for MPNST development and internal PNF tumor load." (PMID 23618374, 2013). "As a tumor suppressor, reduced production of neurofibromin results in the characteristic tumors that define NF1." (PMID 24348581, 2013). "Consistent with the caliper measurements, treatment with MLN8237 resulted in tumour masses that were significantly lower in both the NF1-MPNST and SP-MPNST explants (p<0.01) compared to those of vehicle treated tumours." (PMID 23328114, 2013). "Recently, we identified melanoma-inhibitory activity (MIA; also known as cartilage-derived retinoic acid-sensitive protein (CD-RAP)) as a marker for the internal tumor load in a cohort of 42 patients with NF1." (PMID 23618374, 2013). "NF1 gene is present on chromosome 17 and provides the synthesis of a protein called neurofibromin, functioning as a tumor suppressor." (PMID 23533858, 2013). "Recognizing the similarity of MINST to their peripheral counterparts, MPNST, and their possible relationship with NF1 can help surgeons correctly diagnose and treat this tumor." (PMID 24191220, 2013). "NF1 is a tumor suppressor which has specific-Ras GTPase activating protein activity (GAP) by which it can regulate the mTOR pathway." (PMID 24260221, 2013). "That particular patient's radiographic presentation was similar in severity to ours (likely grade 3-4 OA); however, that case was in a 55-year-old female with NF-1, and she was only treated with tumor resection due to relative knee stability." (PMID 23936704, 2013).
tumor (continued). "Based on the symptoms identified in patients with NF1, it is clear that the NF1 gene plays important roles in cell growth (tumor formation), pigmentation, neuronal activity and function, and bone metabolism." (PMID 22449146, 2012). "Neurofibromin, the product of the NF-1 gene, acts as a tumor suppressor because it inhibits the activity of ras guanosine triphosphatase-activating protein, which regulates cell proliferation and differentiation." (PMID 22824559, 2012). "A good candidate for such a modifier gene influencing tumour development is SUZ12 which is located within the 1.4-Mb NF1 microdeletion region." (PMID 23101500, 2012). "The NF1 gene is a tumor suppressor gene and multiple key pathways are potentially involved in the development of cancer in NF1 cases such as RAS/mitogen-activated protein kinase (MAPK) and AKT/mammalian target of rapamycin (mTOR)." (PMID 22236362, 2012). "This estimation is however based on the observations we made in the 29 patients and implies that the distribution of tumour volumes observed is representative for the whole population of NF1 microdeletion patients." (PMID 23101500, 2012). "Of note, functional studies identified NF1 as a target of the miR-370 and, in agreement with the tumor suppressor activity of NF1, we found that overexpression of miR-370 enhanced the tumorigenic potential of AML cells." (PMID 23077663, 2012). "There appears to be an equal sex distribution in those affected, and the tumor coexists with NF-1 in 44% to 69% of cases." (PMID 22647059, 2012). "Consistent with the tumor suppressor activity of NF1, there was increased proliferation in TF-1 cells transfected with pre-miR-370 in comparison with control cells." (PMID 23077663, 2012). "Of these causes, neoplasms (ICD-9 140-239, excluding 237.7; ICD-10 C00-D48) were the most frequent, accounting for one third of all NF1-associated deaths." (PMID 21439034, 2011). "In contrast, in tumor P072-1N, the 17q-NF1 deletion was present in 49% of the cells while the chromosome 3q deletion was only present in ∼37% of the cells." (PMID 21031597, 2011). "It thus appears likely that MIA expression in NF1 tumours is also regulated by SOX9, as this transcription factor was reported to be required for the survival of MPNST cells." (PMID 21726432, 2011). "In tumor P090-3N chromosome 2 and 17q-NF1 deletions were present in the same proportion of cells (∼49%), suggesting that both alterations affected the same cells." (PMID 21031597, 2011). "NF-1 is characterized by brown skin pigmentation ('café au lait' spots), cutaneous neurofibromas and neoplasms of the peripheral or central nervous system." (PMID 22018031, 2011). "In humans, MIA was expressed in all NF1-related tumours and its serum levels were significantly higher in NF1 patients than in healthy controls." (PMID 21726432, 2011). "He had an extremely high internal tumor load, indicative of the severe disease manifestations resulting from the type-2 NF1 deletion." (PMID 22151963, 2011). "The known mechanisms by which tumor cells evade detection by the human immune system are thought to play a role in the progression to malignancy in patients with NF-1." (PMID 21569290, 2011). "It has been recently shown that NF1 tumours require for their growth the master regulator of cartilage differentiation SOX9." (PMID 21726432, 2011). "NF-1 was confirmed by pathologic evaluation of an excised skin nodule which revealed a neurofibroma." (PMID 20219130, 2010). "The intracellular changes that give rise to this tumor-promoting effect of NF1-haploinsufficiency are unclear." (PMID 20307317, 2010).